SOCS3 (suppressor of cytokine signaling 3)
Diseases named in the same sentence as SOCS3 in open-access papers (continued):
Sharing a sentence is not in itself a finding about the gene and the disease.
glioma (continued). "One of these gene targets is Socs3, which has been shown to be repressed by miR-30 in glioma stem cells and is induced by Interleukin-6 (IL6; Shuai and Liu, 2003)." (PMID 31440139, 2019). "GPM6B promoted the transformation of glioma stem cells and inhibited growth of glioma by suppressing Integrin β1–mediated regulation of β-catenin, while reducing its own degradation through inhibition of the ubiquitinase SOCS3, thereby stabilizing its function in glioma." (PMID 41450963, 2025). "In a summary, our findings first demonstrated that GPM6B not only suppresses glioma stem cell capacity and glioma growth by inhibiting Integrin β1–mediated regulation of β-catenin, but also reduces its own degradation by repressing SOCS3-mediated ubiquitination, thereby stabilizing itself in glioma." (PMID 41450963, 2025). "Finally, in an intracranial glioma model in nude mice, we observed that GPM6B overexpression suppressed intracranial glioma growth, and GPM6B significantly inhibit the functions of β-catenin and SOCS3 in promoting glioma development in vivo." (PMID 41450963, 2025). "Several studies have suggested that SOCS3 acts as a tumor suppressor gene in gliomas." (PMID 34646310, 2021). "In our present study, four progression-related DE IRG (including VEGFA, SOCS3, SPP1, and TGFB2 genes)constituting a signature can perform risk stratification for glioma patients and disclosed that patients with high risk seemed to have an approximate 14.3%-29.8% 5-year survival rate." (PMID 34497663, 2021). "We demonstrated that elevated expression levels of either SOCS1 or SOCS3 could independently predict poor prognosis of patients with primary glioma or GBM." (PMID 32931454, 2020). "However, downregulation of miR-30a can inhibit the JAK/STAT3 pathway by targeting SOCS3 and reducing the tumor-forming ability of glioma stem cells." (PMID 32273831, 2020). "Therefore, we tested the ability of SOCS3−/− macrophages to regulate tumor growth in vivo in an intracranial model of glioma." (PMID 26967393, 2016). "Moreover, we found that deletion of SOCS3 in the myeloid cell population delays intracranial tumor growth and increases survival of mice bearing orthotopic glioma tumors in vivo." (PMID 26967393, 2016). "Furthermore, hypermethylation of CpG islands within the SOCS3 promoter, which blocks SOCS3 induction, is detected in gliomas and hepatocellular tumours and can drive tumour cell migration through enhanced STAT3 and FAK1 activation." (PMID 24886706, 2014). "GPM6B may promote the transformation of glioma stem cells and inhibit growth of glioma by suppressing Integrin β1–mediated regulation of β-catenin, while simultaneously reducing its own degradation through inhibition of the ubiquitinase SOCS3, thereby stabilizing its function in glioma." (PMID 41450963, 2025). "Therefore, we believe that SOCS3 will be a promising prognostic biomarker of patients with glioma." (PMID 34497663, 2021). "Mechanistically, BMX bypasses the suppressor of cytokine signaling 3 (SOCS3)-mediated inhibition of JAK2, whereas targeting of the BMX dampens the JAK2-mediated STAT3 activation, underlying a new molecular basis in which to specifically eliminate the glioma stem cells." (PMID 31130822, 2019). "Recently, there are emerging studies using the CRISPR/Cas9 method in glioma, by which researchers have been able to identify several members responsible for glioma cell growth and proliferation such as USP8 and SOCS3." (PMID 35586564, 2022). "Therefore, SOCS3 may be a new potential prognostic factor that promotes carcinogenesis in gliomas." (PMID 34646310, 2021). "However, the role of SOCS3 in suppressing tumors in gliomas remains unclear." (PMID 34646310, 2021). "In the STAT3 signalling pathway of glioma, miRNAs can directly target STAT3 mRNA, genes closely related to STAT3 activation (PIAS3, SOCS3), and upstream genes of STAT3." (PMID 34425834, 2021).
glioma (continued). "We also found that elevated expression levels of TCEB1, TCEB2, SOCS3 or RNF7 correlate with higher glioma grades, providing new molecular parameters for glioma grading." (PMID 32931454, 2020). "We found that primary glioma patients with higher-than-median expression levels of either SOCS1, SOCS3 or RNF7 had an unfavorable prognosis compared to those with lower-than-median expression levels (P < 0.0001)." (PMID 32931454, 2020). "In the Chinese Glioma Genome Atlas (CGGA) dataset, we found that elevated expression levels of SOCS1, SOCS3, TCEB1, TCEB2 and RNF7 correlated with more advanced WHO grades (grades III and IV) of primary glioma." (PMID 32931454, 2020). "Herein, we sought to determine the role of Suppressor of Cytokine Signaling 3 (SOCS3), a negative regulator of Signal Transducer and Activator of Transcription 3 (STAT3), in GAM functionality in glioma." (PMID 26967393, 2016). "Braden's study demonstrated that myeloid cells lacking SOCS3 expression exhibit augmented and sustained production of proinflammatory M1-type cytokines upon exposure to glioma-derived conditioned media in vitro." (PMID 40838069, 2025). "Notably, overexpression of miR-30 is observed in glioma stem cells; downregulation of miR-30 reduces SOCS3 suppression, activating the JAK/STAT3 signaling pathway, thus confirming the regulatory role of the miR-30/SOCS3/JAK/STAT3 axis." (PMID 40642530, 2025).
pancreatic cancer (28 papers, 2015 to 2025). "The expression of the proto-oncogene Kras in the pancreas activates the Stat3/Socs3 signaling pathway, which relies on IL-6 and its downstream signaling pathways, ultimately promoting pancreatic cancer development." (PMID 39981173, 2025). "Let-7 also inhibits the progression of pancreatic cancer cells by upregulating the suppressor of cytokine signaling 3 (SOCS3) expression, leading to the inhibition of STAT3 phosphorylation." (PMID 38139352, 2023). "As one of the most key negative regulating factors of the JAK/STAT signaling pathway, SOCS3 downregulated cancer progression in lung and pancreatic cancers, which are similar to our analysis in vitro." (PMID 34926570, 2021). "By recruiting EZH2, lncRNA UCA1 regulates the methylation of SOCS3 protein, reduces the expression of SOCS3, and promotes the Gem resistance of pancreatic cancer." (PMID 34868904, 2021). "IL-6/STAT3 signaling can promote pancreatic cancer growth and metastasis, which induce suppressor of cytokine signaling 3 (SOCS3) methylation through DNA methyltransferase 1 (DNMT1)." (PMID 33406733, 2021). "The results of qRT-PCR showed higher expression of lncRNA UCA1 and EZH2 and lower SOCS3 expression in pancreatic cancer tissues than that in adjacent normal tissues." (PMID 34868904, 2021). "Further, we observed that SOCS3 underexpression occurred in pancreatic cancer and it was negatively correlated with EZH2." (PMID 34868904, 2021). "Corroborating previous documentation, our results confirmed through gain- and loss- of function assays that lncRNA UCA1 inhibited the expression of SOCS3, thereby enhancing the malignant phenotypes, tumorigenesis and Gem resistance of pancreatic cancer cells." (PMID 34868904, 2021). "This study aims to investigate roles of lncRNA UCA1-loaded exosomes secreted by pancreatic stellate cells (PSCs) in Gemcitabine (Gem) resistance of pancreatic cancer under hypoxia, which involves the methylation of SOCS3 and EZH2 recruitment." (PMID 34868904, 2021). "It was shown in in vivo and in vitro experiments of a previous study, upregulated GAS5 promoted the expression of SOCS3, thus inhibiting the growth, metastasis, and Gem resistance of pancreatic cancer." (PMID 34868904, 2021). "SOCS3 overexpression has been observed to suppress malignant behaviors and Gem resistance of pancreatic cancer cells." (PMID 34868904, 2021). "Differential expression analysis on the GSE32676 and GSE16515 datasets showed that SOCS3 was poorly expressed in pancreatic cancer samples." (PMID 34868904, 2021). "As previously discussed, the lncRNA GAS5 also targets miRNA-221 and can reduce its levels in pancreatic cancer cells resulting in increased sensitivity to gemcitabine via relief of suppression of the miRNA-221 target SOCS3." (PMID 31979312, 2020). "A report about the regulation of SOCS3 in pancreatic cancer cells found out that, the restoration of miRNA let-7 promoted the expression of SOCS3 and then impeded the activation of STAT3." (PMID 31222560, 2019). "For example, in pancreatic cancer SOCS3 expression correlates with a better prognosis and overexpression of SOCS3 limits tumor growth, while SOCS3 silencing by promoter methylation has opposite effects." (PMID 29020964, 2017). "According to another study, let-7 downregulates STAT3 phosphorylation in pancreatic cancer cells by increasing SOCS3 expression." (PMID 25856466, 2015). "In addition to this complication, miR-203 has dual functions in pancreatic cancer, limiting cell proliferation while simultaneously promoting apoptosis via precise changes in the expression of suppressor of cytokine signaling 3 (SOCS3)." (PMID 39087024, 2024). "LncRNA UCA1 was highly expressed, while SOCS3 was poorly expressed in pancreatic cancer tissues." (PMID 34868904, 2021). "It indicates that SOCS3 methylation is related to the malignant degree of pancreatic cancer." (PMID 32751889, 2020).
pancreatic cancer (continued). "Therefore, the present study set out to elucidate the roles of lncRNA UCA1 loaded in PSC-derived exosomes in Gem resistance of pancreatic cancer under hypoxia, and to identify the downstream mechanisms involving histone methylation in SOCS3 gene region and EZH2 recruitment." (PMID 34868904, 2021). "Finally, we proceeded to determine whether HPSC-EXO affects the chemotherapy resistance of pancreatic cancer through the lncRNA UCA1/EZH2/SOCS3 axis." (PMID 34868904, 2021). "The exosomes were isolated from PSCs and hypoxic PSCs (HPSCs), and co-cultured with pancreatic cancer cells transduced with manipulated lncRNA UCA1, EZH2, and SOCS3." (PMID 34868904, 2021). "Another study demonstrated that HDAC5 recruited macrophages to the tumor microenvironment through the Suppressor of cytokine signaling 3 (Socs3)/C-C motif chemokine ligand 2 (CCL2) axis and promoted pancreatic cancer via TGF-β-dependent paracrine signaling." (PMID 34178647, 2021). "Epigenetic silencing of SOCS3 (suppressor of cytokine signaling 3) has a carcinogenic effect and SOCS3 promoter methylation has been observed in pancreatic cancer." (PMID 32751889, 2020). "In a murine model of pancreatic cancer cachexia, the JAK/STAT/SOCS3-dependent intracellular pathway plays an essential role in pathogenesis, since its pharmacological inhibition attenuates cachexia progression in a lethal pancreatic cancer model." (PMID 31013615, 2019). "• siRNA-mediated SOCS3 knock-down in normal pancreatic HPDE6C7 cells and plasmid-transfected SOCS3 over-expression in pancreatic cancer cells lead to the obvious promotion and inhibition of Reg3A-induced cell proliferation, respectively." (PMID 31921694, 2019). "Targeting IL-6 in acupuncture treatment of pancreatic cancer is a promising research direction, which may involve IL-6/STAT3 axis, DNMT1-induced SOCS3 methylation, NRP-1, etc." (PMID 36105933, 2022). "In addition, Pearson’s correlation analysis showed that SOCS3 expression was negatively correlated with the expression of EZH2 (r = -0.75, p < 0.01) and lncRNA UCA1 (r = -0.73, p < 0.01) in pancreatic cancer tissues." (PMID 34868904, 2021). "Under hypoxic conditions, exosomes secreted by hypoxia-induced PSCs deliver lncRNA UCA1 into pancreatic cancer cells, where lncRNA UCA1 recruits EZH2 and regulates histone methylation level in SOCS3 gene region, thereby augmenting pancreatic cancer resistance to Gem." (PMID 34868904, 2021). "And another report demonstrated that activated interleukin-6/Stat3 signaling could induce suppressor of cytokine signaling 3 (SOCS3) methylation via DNMT1, resulting in pancreatic cancer growth and metastasis." (PMID 28360411, 2017). "Although IL-6 and Socs3 mRNA expression did not significantly change in the gastrocnemius muscle of RM9-bearing mice, IL6ra was increased similar to what others have observed in a murine pancreatic cancer cachexia model." (PMID 35785158, 2022).
Arthritis (26 papers, 2006 to 2025). Inflammation of a joint. "In vivo miR-34a deficiency led to attenuation of antigen-induced experimental arthritis that was associated with an increased expression of the miR-34a target pathway Axl/Socs-3 in joint tissue." (PMID 28639625, 2017). "Genes known to be involved in autoimmune response and arthritis, such as those encoding Galectin-3, Versican, and Socs3, were identified and validated by quantitative TaqMan RT-PCR analysis using independent blood samples." (PMID 16507131, 2006). "Once (3S)-vestitol up-regulated SOCS3 expression, it may be a relevant agent to reduce alveolar bone loss in an inflammatory condition such as arthritis and periodontal disease." (PMID 35631379, 2022). "In mouse models of inflammatory arthritis, SOCS3 deficiency in the hematopoietic compartment caused more severe joint inflammation associated with elevated levels of IL-6 and G-CSF, increased neutrophil numbers and constitutively activated CD4+ T cells and macrophages." (PMID 34604264, 2021). "A previous study found that CIA mice overexpressing SOCS3 had significantly reduced arthritis severity and IL-6 production." (PMID 38966637, 2024). "On the other hand, Socs3 deletion in hematopoietic and endothelial cells increases osteoclast numbers and bone destruction in arthritis." (PMID 36591261, 2022). "This is an interesting observation regarding that STAT3-regulated SOCS3 expression in CD4+ T cells has been shown to be elevated in a cohort of 161 treatment-naïve early arthritis patients and in PBMCs from patients with active RA." (PMID 34630419, 2021). "In studies on arthritis, SOCS3 was involved in defense against inflammation and articular tissue repair." (PMID 34067297, 2021). "In a study using mice with experimental arthritis, it was found that compared with the control group, injection of recombinant adenovirus carrying SOCS3 cDNA in the joint cavity can significantly reduce the severity of arthritis and joint swelling." (PMID 33072096, 2020). "Overexpression of TAM ligands is known to increase SOCS3 levels and contributes to dampen murine arthritis." (PMID 30713533, 2019). "In this regard, it has been reported that SOCS3 is the key mediator of the inhibitory effects of IL-10 in macrophages stimulated with LPS, and in an in vivo model of collagen induced arthritis." (PMID 31214200, 2019). "Silencing SOCS3 in mice rendered a high clinical arthritis scores after injection with minicircle DNA expressing IL23." (PMID 30487798, 2018). "The role of SOCS-3 in arthritis has been studied in animal models by a few groups and the existing data support the idea that SOCS-3 has a protective role in arthritis." (PMID 27716333, 2016). "Understanding the roles of SOCS3 in inflammatory diseases of bone and joints such as arthritis, osteomyelitis, and periodontal diseases is critical to revealing insights into signaling pathways that can be manipulated in potential therapeutic approaches." (PMID 24454312, 2014). "This review provides an overview of the important role of SOCS3 in inflammatory responses of various bone cells and in bone inflammatory disorders such as periodontal disease and arthritis." (PMID 24454312, 2014). "qPCR confirmed that two of those genes (Fcgr1 and Socs3), which were selected for validation from the osteoclast differentiation pathway, showed significant association with the CCR2hi OCP subset and were further increased in arthritis." (PMID 36591261, 2022). "Similarly, SOCS3 expression in human arthritic chondrocytes contributed to cartilage damage during arthritis." (PMID 34604264, 2021). "For example, SOCS-3 has been reported as a key mediator in the inhibitory effects of IL-10 in macrophages stimulated with LPS and in an in vivo model of collagen-induced arthritis." (PMID 24260222, 2013). "To investigate the link between increased IL-10 production and suppression of arthritis we determined the mRNA levels of the suppressors of cytokine signalling 1 and 3 (SOCS1 and SOCS3)." (PMID 23166758, 2012).
Arthritis (continued). "One recent study reported that tacrolimus significantly increased SOCS3 mRNA levels in affected joints in an arthritis mouse model induced by K/BxN serum when compared to non-treated arthritic mice." (PMID 24454312, 2014). "The enhanced synovial Socs3 expression could be an indication that the MER-specific antibodies evoked a local anti-inflammatory response, but if so, it appeared to be overruled during arthritis." (PMID 29706963, 2018). "In addition, tacrolimus significantly induced SOCS3 mRNA expression in affected joints of the arthritis model compared to the non-treated arthritic animals (P <0.05)." (PMID 23406906, 2013).